CDKN2B (cyclin dependent kinase inhibitor 2B)
Diseases named in the same sentence as CDKN2B in open-access papers (continued):
Sharing a sentence is not in itself a finding about the gene and the disease.
tumor (continued). "For example, CCND1 and CTTN showed amplification in more than 9 tumor foci, while CDKN2A and CDKN2B exhibited deletion in more than 6 tumor foci." (PMID 38956687, 2024). "The patient-derived tumor sample Gb14_pr showed the deletion of CDKN2A and CDKN2B and Gb15_pr reported the deletion of 1p." (PMID 38534332, 2024). "We biopsied tumor specimens from five patients with PR and PD to detect the protein and mRNA levels of RB1, CDKN2B, PCNA, and MCM7." (PMID 37781033, 2023). "Most tumor cells have MTAP, P16 and other tumor suppressor genes located on 9P21 such as CDKN2A and CDKN2B making it a poor target for therapeutic regimens." (PMID 36913304, 2023). "The current study results revealed the upregulation of four genes including ADAMTS18, CDKN2B, and FHIT as tumor suppressors and WNT5B as an oncogene in the patients." (PMID 35176183, 2022). "Focally deleted regions identified the tumour-suppressor genes RHOA at 3p21, CDKN2A and CDKN2B at 9p21, RAD51B, MAX, DICER1, BCL11B, NKX2-1, CCNB1IP1 and BAZ1A at 9q33." (PMID 34980126, 2022). "The MTAP/CDKN2A locus encompasses two functional tumour suppressor genes, CDKN2A and CDKN2B, that are known to play a role in familial and sporadic melanoma risk, as well as a number of other genes with potential involvement in this disease." (PMID 35357426, 2022). "Transcriptions of CDKN2A, CDKN2B, CDKN2B_AS1, and MTAP were included because these genes are located at 9p21.3, and they are also potential tumor suppressors." (PMID 36313281, 2022). "Cyclin-dependent kinase inhibitor 2B (CDKN2B, also known as p15), is a well-known tumor suppressor that is deregulated in various tumors." (PMID 33601338, 2021). "Following tumor excision, immunohistochemical analysis showed decreased DNMT3B and increased CDKN2B expression in tumors overexpressing miR-29b." (PMID 33601338, 2021). "In high PDIA3 expression samples, frequently amplified genomic peaks were detected in oncogenic drivers, including PDGFRA, EGFR and CDK4; in addition, tumor suppressor genes, such as CDKN2A/CDKN2B and PTEN were observed a deletion peak." (PMID 32687065, 2020). "There are three loci in human chromosome 9p21 as tumor suppressor genes including, CDKN2A (p16INK4a), CDKN2A (p14ARF), and CDKN2B (p15INK4b)." (PMID 33282730, 2020). "Other co-alterations that have a potential impact on tumor biology include KEAP1 (4%) and combined CDKN2A/CDKN2B (4%)." (PMID 32295619, 2020). "Consistent with the role of SAM as a methyl donor, NCT-503 decreased DNA and histone methylation, and led to the re-expression of ID4, KLF4, CDKN2B and TXNIP tumor suppressors." (PMID 32138178, 2020). "Two important tumor-suppressor genes, CDKN2A (chromosome 9p21.3) and CDKN2B (chromosome 9p21.3), were deleted in all clusters except for II." (PMID 33194713, 2020). "Chromosome 9p21.3 resides in a region distant from known coding regions, with tumor suppressor genes of cyclin-dependent kinase inhibitors (CDKN2A and CDKN2B) and methylthioadenosine phosphorylase." (PMID 30921371, 2019). "MSD-MSCs undergo premature cell-cycle arrest due to a significant upregulation of cyclin-dependent kinase inhibitor 2B (CDKN2B) compared to healthy counterparts, highlighting a possible role of MSCs in the control of tumor growth." (PMID 31861268, 2019).
tumor (continued). "Given that promoter hypermethylation is an alternative method to inactivate tumor-suppressor genes in a variety of malignancies, we evaluated the methylation status of 93 CDKN2A and CDKN2B genes." (PMID 30635552, 2019). "Accordingly, the INK4b/ARF/INK4a locus is deleted or downregulated in about 40% of human cancers, mainly related to the tumor suppressive function of CDKN2A and CDKN2B; conversely, ANRIL itself shows a pro-oncogenic activity." (PMID 31694342, 2019). "Although the CDKN2A/B locus is deleted or silenced in approximately 40% of human cancers, related to the tumor suppressive actions of CDKN2A and CDKN2B, ANRIL itself has pro-oncogenic properties." (PMID 30087655, 2018). "Some research has demonstrated that upregulating the expression of CDKN2B can promote the G1 retardation of HepG2/DDP, inhibit tumor cell proliferation, and enhance the accumulation and retention of chemotherapeutic drugs in cells." (PMID 29299129, 2017). "ANRIL is thought to regulate the INK4/ARF tumor suppressor locus; therefore, we examined expressions of two CDKN2A transcripts (p16INK4A and p14ARF) and one CDKN2B transcript (p15INK4B)." (PMID 27055116, 2016). "Recent reports demonstrate promoter methylation of tumor-related genes, including MGMT, CDKN2B and RASSF1." (PMID 26675260, 2016). "The most frequently methylated gene was p14ARF—methylated in 31.82 % (14/44) of tumor samples, followed by RASSF1A methylated in 27.27 % (12/44) and CDKN2B (p15INK4B) which was methylated in 25.00 % (11/44) of cases." (PMID 25648363, 2015). "The relative expression of the genes CDKN2A, CDKN2B, and RB1 was significantly decreased in all the examined tumor grades." (PMID 26317630, 2015). "Among the CIMP genes are three well-known tumor suppressors: p14ARF, p16INK4A (also known as CDKN2A), and p15INK4B (also known as CDKN2B)." (PMID 24623306, 2014). "In the same LD block with this gene are CDKN2A (P16), CDKN2B (P15) and ARF (P14), which are all recognized tumour suppressor genes." (PMID 24676469, 2014). "For example, tumor suppressor genes, such as p15 (CDKN2B), p16 (CDKN2A), p57 (CDKN1C), p73 (TP73), SHP-1 and DAPK, are frequently hypermethylated and related to tumor progression in lymphoid malignancies." (PMID 24252620, 2013). "TAGCNA identifies SCEs that are known to be involved with proto-oncogenes (e.g. EGFR, CDK4) and tumor suppressor genes (e.g. CDKN2A, CDKN2B), and provides many additional SCEs with potential biological relevance in these data." (PMID 22815924, 2012). "The human chromosome 9p21 locus has three different genes that have tumor suppressor functions, namely cyclin-dependent kinase inhibitor 2A (CDKN2A): p16INK4a and p14ARF (INK4a/ARF) and CDKN2B: p15INK4b, respectively." (PMID 21892281, 2008). "Hemizygous deletion of the region harbouring the CDKN2A and CDKN2B loci was identified in two tumours by means of fluorescent in situ hybridisation and MTAP was present by immunostaining in all but one tumour analysed." (PMID 15305192, 2004). "No significant change was detected for CDKN2A/p16INK4a, CDKN2A/p14ARF,CDKN2B/p15INK4b, MTAP, IFNA and IFNB mRNAs in tumours with 9p21–23 LOH when compared to those with retained heterozygosity." (PMID 15305192, 2004). "Other somatic mutations associated with VTE independent of tumor type include KRAS, STK11, MET, KEAP1, CTNNB1, and CDKN2B." (PMID 39851266, 2025).
tumor (continued). "A study confirming the occurrence of LOH most frequent on chromosome 9 found four patients with biallelic deletion 9p21.3 (three of them had LOH) of the tumor suppressor gene cluster (CDKN2A, CDKN2BAS1, CDKN2B, and DMRTA1), which is fully consistent with our research." (PMID 40805197, 2025). "Desirable criteria are MAPK pathway gene alterations and homozygous deletion or mutation of CDKN2A and/or CDKN2B (both present in this tumour), as well as mutation of ATRX and anaplastic histological features (both not present in this tumour)." (PMID 39427038, 2024). "Deep deletions of chromosome regions containing FBXW7, CDKN2A, CDKN2B, and MTAP could be identified in the MPM693 patient-derived cell line and the corresponding tumor." (PMID 37345150, 2023). "CDKN2A and CDKN2B deletions were found in the MPM665 patient-derived cell line but not in the corresponding tumor." (PMID 37345150, 2023). "Only one tumor (1/9, 11%) demonstrated focal amplification of PDGFRA on chromosome 4q12, and only one tumor (1/9, 11%) demonstrated focal homozygous/biallelic deletion of CDKN2A and CDKN2B on chromosome 9p21." (PMID 38079020, 2023). "High frequency of genetic alterations of tumor suppressors (e.g., PTEN and CDKN2A/CDKN2B) and oncogenes (e.g., PDGFA and EGFR) suggested that these cancer driver genes might be responsible for initiation of mGBM but not contribute to the progression of mGBM." (PMID 34987659, 2022). "The presence of CDKN2A/CDKN2B biallelic and monoallelic loss was tested employing FISH in 18 tumor samples with no discrepancies observed when compared to NGS." (PMID 35372034, 2022). "Furthermore, TET3 levels positively correlated with CDKN2B, ZIC2, and miR-196a levels, which appear to have anti-leukemic effects, thus suggesting a tumor suppressive role for TET3 in AML." (PMID 36059621, 2022). "Along with CDKN2A, other INK4 family members, CDKN2B, CDKN2C, and CDKN2D, also showed a good ability to distinguish tumor from normal tissue, particularly CDKN2C, suggesting that they can be used as biomarkers for the screening, diagnosis, and prognosis prediction of HCC." (PMID 35771229, 2022). "In addition to the focal deletion region, nearby regions within 9p21.3 also showed high frequency of deletion involving two tumor suppressors (CDKN2A, CDKN2B), MTAP and a cluster of type I IFN genes." (PMID 31311932, 2019). "Additionally, the region harboring the cyclin D1 (CCND1) oncogene was amplified and the region harboring the tumor suppressor genes, Cyclin Dependent Kinase Inhibitor 2A (CDKN2A) and CDKN2B, was deleted in both pre- and post-CCRT samples." (PMID 31097034, 2019). "To assess the accuracy of the information and patterns gleaned from CNVseq, we conducted three separate examinations:A)We examined genome-wide gene expression data from these tumours (DASL HT12.4 array) to compare gene expression in CDKN2A, CDKN2B, MTAP and PTEN.." (PMID 31222134, 2019). "Four variants [c.1393G>C (p.Gly465Arg) and c.2179G>A (p.Gly727Arg) in GLI3, c.360C>T (p.Ala120=) in CDKN2B and c.2794G>A (p.Val932Met) in PALB2] were identified in tumours that developed recurrence and in all cases were present both in primary and recurrent samples." (PMID 30344923, 2018). "Adjacent tumour suppressor pairs (e.g., CDKN2A/CDKN2B, BIRC2/BIRC3, HELQ/FAM175A...) may be especially rewarding targets for homozygous deletion in some cases, as two mutation events can abolish all tumour suppressor activity." (PMID 29089486, 2017). "Earlier report showed that miR-31 is located at the chromosome 9q21.3, and this locus is very close to the locations of tumor suppressors, CDKN2A and CDKN2B, that is frequently deleted in many cases of cancers, which may result in down-regulation of miR-31." (PMID 25797269, 2015).
tumor (continued). "The genes CDKN2A, CDKN2B, and RB1 function as tumor suppressors; their decreased expression occurs via several mechanisms, including methylation, and contributes to the development of neoplasias." (PMID 26317630, 2015). "In addition, the CMIs of CDKN2B, RASSFIA, DLC1 and CCND2 in the OCSPCs from ascites were significantly higher than those in the OCSPCs from tissues (p = 0.001) or bulk tumor cells (p = 0.038)." (PMID 26597084, 2015). "This hypothesis is supported by the presence of the cyclin-dependent kinase inhibitor 2B (CDKN2B) and 2C (CDKN2C) tumor suppressor genes in the identified gene set." (PMID 23049694, 2012). "Moreover, many unique mutations were only found in CSF samples, but not in the tumor tissue and plasma samples, which includes FH mutation, SETD2 mutation, WT1 mutation, CDKN2A mutation, CDKN2B mutation." (PMID 36937524, 2023). "Experiments in mice have shown that the Cdkn2b also exhibits a tumor suppressor role in MPM, as its deletion concomitant with Cdkn2a further accelerates MPM development (our unpublished results) offering a rationale for the predominant deletion of all three tumor suppressors in this locus in MPM." (PMID 32117751, 2020). "Additionally, to sustain proliferative signalling (right side), the tumour oncogene CCND1, probably influenced by the co-expressed gene NCOA1/3 as well as the suppressors CDKN2A and CDKN2B, which govern the cell cycle, were genetically altered to enhance cancer cell growth in both smoking subgroups." (PMID 32455963, 2020). "Among the tumor-related genes, the top amplified genes included ERBB2 (17q21), MYC (8q24), GNAS (20q13), EGFR (7p11), ZNF217 (20q13), CCNE1(19q12), NCOA3 (20q13), and CDK6 (7q21), and the most frequently deleted genes were CDKN2A (9p21), CDKN2B (9p21), KIT (4q12), SMAD4 (18q21), and FGFR1 (8p12)." (PMID 31541076, 2019). "Although loss of Ptprd and Cdkn2a may be targeted in cancer, our data does not rule out the potential role of other tumor suppressors on chromosome 9p, including Cdkn2b." (PMID 25138050, 2014). "This microsatellite is 8 kb away from CDKN2A exon 1β and 3 kb from CDKN2B exon 2, which could not be detected in the tumour DNA." (PMID 19643034, 2009). "When using DNA from tumour as template, no PCR products could be obtained for CDKN2B exons 1 and 2 and their flanking intronic sequences." (PMID 19643034, 2009). "Furthermore, recent studies have identified multiple additional pathways through which ARNT may contribute to tumor initiation, progression, and drug resistance, including the fibronectin/integrin β1/FAK, Myc/Miz/CDKN2B, NF-κB, p38α-MAPK, and canonical AHR/ARNT signaling pathways." (PMID 39684472, 2024). "However, CDKN2B is also repressed at low O2 levels in HCT116 cells, although hypoxia induces cell cycle arrest in these cells, suggesting that it is the combined transcriptional changes in cell cycle regulatory factors that will determine the final proliferative characteristics of a tumor cell." (PMID 24618291, 2014). "The relationship of CDKN2A and CDKN2B expression with the corresponding SCNA levels seemed to indicate that complex pathways regulated their transcription levels and that their tumor suppressor properties were not evident in ccRCC." (PMID 35677048, 2022).
tumor (continued). "Due to intratumoral heterogeneity of tumor tissue and clonal enrichment of PDCs, some PDCs were not completely concordant with corresponding tumor tissue in detecting the CNVs of CDKN2A and CDKN2B." (PMID 31700061, 2019). "We did not see upregulation of reported tumour-suppressor genes, such as CDKN2A, CDKN2B and PML, and factors for neuronal differentiation, such as SMARCC1 and DLX2, in our microarray analysis." (PMID 26838672, 2016). "In our study, the genes CDKN2B, CDKN2A, and RB1 were not methylated and hipoexpressed in all the tumor grades analyzed." (PMID 26317630, 2015). "CDKN2B's neighbor, cyclin-dependent kinase inhibitor 2A (CDKN2A), functions similarly to inhibit Cdk4 and is a known tumor suppressor, but is not detectably expressed in either normal or tumor tissue." (PMID 20174472, 2010).